ZNF280A (zinc finger protein 280A)
Description:
May function as a transcription factor.
Synonyms: SUHW1; ZNF280; ZNF636; 3'OY11.1
Tractability: No criterion of Open Targets' tractability assessment is met for any kind of drug.
Gene: Protein-coding gene on chromosome 22 (22,513,736 to 22,520,270, reverse strand). Ensembl gene ENSG00000169548.
Subcellular location: Nucleus
Subcellular location (Human Protein Atlas): Nucleoplasm
Gene Ontology:
Molecular function: protein binding; DNA-binding transcription factor activity, RNA polymerase II-specific; RNA polymerase II cis-regulatory region sequence-specific DNA binding
Biological process: regulation of DNA-templated transcription; regulation of transcription by RNA polymerase II
Cellular component: nucleus
Genetic constraint (gnomAD): Loss-of-function variants: 26 observed, 36.83 expected, observed/expected ratio (o/e) 0.71, 90% interval 0.52 to 0.98. The upper end of that interval is the gene's LOEUF score, 0.98, which puts it in group 4 of 6, group 1 being the genes least tolerant of losing a copy. Missense variants: 636 observed, 664.82 expected, observed/expected ratio (o/e) 0.96, 90% interval 0.9 to 1.02. Synonymous variants: 225 observed, 239.3 expected, observed/expected ratio (o/e) 0.94, 90% interval 0.84 to 1.05.
Homologues: Orthologues: chimpanzee ZNF280A (97% identical), macaque ZNF280A (88% identical), rabbit ZNF280A (62% identical). Paralogues in human: ZNF280B (63% identical), ZNF280D (47% identical), ZNF280C (41% identical), ZBTB49 (13% identical), ZBTB21 (12% identical), FEZF1 (12% identical), GFI1 (11% identical), BCL6 (11% identical), FEZF2 (11% identical), PRDM13 (9% identical), ZBTB7B (9% identical), BCL6B (9% identical), and 16 more.
Diseases named in the same sentence as ZNF280A in open-access papers:
ZNF280A is named in the same sentence as 16 diseases in open-access papers, as found by Europe PMC text mining. Sharing a sentence is not in itself a finding about the gene and the disease. The quoted sentences say what the papers report.
colorectal cancer (3 papers, 2021 to 2024). A primary or metastatic malignant neoplasm that affects the colon or rectum. "Expression of ZNF280A in colorectal cancer tissues and para-carcinoma tissues in immunohistochemistry." (PMID 36059657, 2022). "Correlation of ZNF280A expression with clinical pathological characteristics in patients with colorectal cancer." (PMID 36059657, 2022). "RPS14 overexpression promoted the development of colorectal carcinoma, and RPS14, a downstream target of zinc finger protein 280 A (ZNF280A), was upregulated in melanoma cells and has a co-binding site for YAP and β-catenin via LEF1/TEAD." (PMID 38388496, 2024).
lung adenocarcinoma (3 papers, 2021 to 2022). A carcinoma that arises from the lung and is characterized by the presence of malignant glandular epithelial cells. "ZNF280A may promote the development of lung adenocarcinoma by interacting with EIF3C, thus implying that EIF3C may have a potential role in lung cancer." (PMID 36157221, 2022).
lung carcinoma (2 papers, 2022 to 2025). "Moreover, consistent with prior reports in colorectal and lung cancers where ZNF280A promotes tumorigenesis via PI3K/AKT activation, our data demonstrate a conserved yet context-specific regulatory paradigm in OC, coupling metabolic remodeling to cell proliferation and survival." (PMID 41338461, 2025).
benign ovarian tumor (1 paper, 2025). "Quantitative analysis indicated that 51.4% (55/107) of tumor tissues exhibited high ZNF280A expression, which was significantly higher than that in benign ovarian tumor tissues (p < 0.001)." (PMID 41338461, 2025). "Representative IHC images showed markedly stronger ZNF280A staining in ovarian cancer tissues than in benign ovarian tumor tissues." (PMID 41338461, 2025).
cervical cancer (1 paper, 2022). A primary or metastatic malignant neoplasm involving the cervix. "A total of 9222 overlapping mutations were found among patient original cervical cancer (F0) and F2-, F3-PDX, of which including the Zinc-Finger Protein family genes, such as ZNF275 and ZNF280A." (PMID 36076209, 2022).
lentivirus infection (1 paper, 2022). Virus diseases caused by the Lentivirus genus. "We first engineered HCT116 and RKO cells that stably silenced ZNF280A by endogenously knocking down ZNF280A via lentivirus infection, and subsequently evaluated the efficiency of transfection by fluorescence imaging, and assessed the knockdown efficiency by qPCR and western blotting." (PMID 36059657, 2022).
Lymphatic Metastasis (1 paper, 2022). Transfer of a neoplasm from its primary site to lymph nodes or to distant parts of the body by way of the lymphatic system. "High level of ZNF280A was positively correlated with clinical characteristics including pathological stage (P = 0.010) and lymphatic metastasis (P = 0.004)." (PMID 36059657, 2022).
ovarian carcinoma (1 paper, 2025). A malignant neoplasm originating from the surface ovarian epithelium. "To elucidate how the ZNF280A/ACRV1 axis regulates ovarian cancer progression, we performed gene set enrichment analysis (GSEA)." (PMID 41338461, 2025). "To investigate the expression pattern of ZNF280A in OC, we analyzed RNA sequencing data from The Cancer Genome Atlas Ovarian Cancer (TCGA-OV) cohort." (PMID 41338461, 2025). "Collectively, our findings establish ZNF280A as a key regulator of metabolic reprogramming in OC through the CUX2–ACRV1–PI3K/AKT axis, highlighting this pathway as a potential therapeutic target in ovarian cancer." (PMID 41338461, 2025).
tumor (3 papers, 2021 to 2025). "Collectively, these results underscore the potential of ZNF280A as a prognostic biomarker in OC, with its increased expression intimately linked to the malignancy of the tumor." (PMID 41338461, 2025). "ZNF280A dysregulation has been linked to tumor progression and metastasis in bladder cancer, regulation of cell cycle and apoptosis in lung adenocarcinoma, and activation of the PI3K/AKT signaling pathway in colorectal cancer." (PMID 41338461, 2025). "Our findings uncovered significant positive correlations between ZNF280A expression and clinical grade (p < 0.001), tumor size (p < 0.001), and tumor-node-metastasis staging (p < 0.05), implying that ZNF280A upregulation parallels disease progression." (PMID 41338461, 2025). "The results revealed a significant upregulation of ZNF280A in tumor tissues compared with adjacent normal ovarian tissues (p < 0.001), suggesting a potential role in OC progression." (PMID 41338461, 2025). "In this study, we demonstrated that ZNF280A was remarkably upregulated in CRC tissues, which was meaningfully associated with the tumor progression and poor prognosis in CRC patients." (PMID 36059657, 2022). "ZNF280A was remarkably upregulated in CRC tissues, which was meaningfully associated with tumor progression and poor prognosis in patients with CRC." (PMID 36059657, 2022). "Herein, ZNF280A, a member of the zinc finger protein family carrying two consecutive Cys2His2 zinc finger domains, was shown by us to act as a tumor driver in LUAD." (PMID 33414445, 2021). "Analysis of clinical specimens revealed the potential of ZNF280A as an indicator for tumor progression and poor prognosis of LUAD patients." (PMID 33414445, 2021). "The immunohistochemical analysis of ZNF280A in LUAD indicated its positive correlation with tumor grade, pathological stage and lymphatic metastasis, and negative relationship with patients’ survival." (PMID 33414445, 2021). "High level of ZNF280A was positively correlated with clinical characteristics including tumor grade (P = 0.001), pathological stage (P = 0.011) and lymphatic metastasis (P = 0.016)." (PMID 33414445, 2021). "In conclusion, a novel LUAD tumor promotor, ZNF280A, was identified." (PMID 33414445, 2021). "High expression of ZNF280A in LUAD tumor tissues was significantly correlated with the advanced grade of tumors and could forecast relatively shorter survival period." (PMID 33414445, 2021). "It was thus deduced that ZNF280A may act as a tumor driver in LUAD by influencing EIF3C expression." (PMID 33414445, 2021). "Biologically, the ZNF280A/ACRV1 axis functions as a metabolic switch that enhances glycolytic capacity, enabling OC cells to adapt to hypoxia and nutrient stress within the tumor microenvironment." (PMID 41338461, 2025). "Herein, we recognize ZNF280A, a zinc finger protein with C2H2 domain, as a potential tumor promotor and prognostic indicator in LUAD." (PMID 33414445, 2021). "On the other hand, although ZNF280A contains two consecutive C2H2-type zinc finger domain transcription factors, there are few studies on its tumor biology." (PMID 33414445, 2021). "Moreover, ZNF280A knockdown was also expounded to influence migratory capacity of LUAD cells, highlighting its potential role in tumor metastasis." (PMID 33414445, 2021).
cancer (2 papers, 2022 to 2025). A tumor composed of atypical neoplastic, often pleomorphic cells that invade other tissues. "Our findings, which demonstrate the upregulation of ZNF280A in OC tissues and its association with poor survival outcomes, align with previous studies that have identified ZNF280A as a potential oncogene in various cancer types." (PMID 41338461, 2025). "While previous research has hinted at the involvement of ZNF280A in cancer progression, its specific role in OC and its modulation of aerobic glycolysis have remained largely unexplored." (PMID 41338461, 2025). "The high expression of ZNF280A in CRC was recently reported to be associated with proliferation and tumorigenesis of cancer cells via inactivating the Hippo-signaling pathway." (PMID 36059657, 2022). "However, ACRV1, a relatively understudied protein in cancer, emerges as a key player in our study, positively regulating ZNF280A and contributing to OC progression." (PMID 41338461, 2025). "However, our understanding about the biological role of ZNF280A in cancers is far from enough." (PMID 36059657, 2022). "Immunohistochemistry (IHC) analysis of CRC (n=98) and para-carcinoma (n=72) tissues showed the presence of ZNF280A in CRC tissues, and further manifested the higher level of ZNF280A in CRC tissues relative to that in para-carcinoma tissue." (PMID 36059657, 2022).
hematologic malignancies (1 paper, 2022). "The correlation between ZNF280A and hematologic malignancies has been previously reported." (PMID 36059657, 2022).
ZNF280A also shares sentences with these, for which no sentence is quoted: gastric cancer (1 paper); glioma (1); infection (1); melanoma (1); nasopharyngeal carcinoma (1).